LRP1 (LDL receptor related protein 1)
Diseases named in the same sentence as LRP1 in open-access papers (continued):
Sharing a sentence is not in itself a finding about the gene and the disease.
atherosclerosis (continued). "Mice lacking LRP1 in vascular smooth muscle cells (vSMCs) are characterized by a susceptibility to develop atherosclerosis." (PMID 29540796, 2018). "Mice lacking Lrp1 in macrophages have more extensive atherosclerosis when crossed into an LDL receptor-deficient mouse." (PMID 30518764, 2018). "This ability to promote or suppress inflammatory processes that are involved in the early phases of atherosclerosis may explain the apparent dual action of LRP1." (PMID 29914093, 2018). "It is well known that the development of atherosclerosis is a complex process involving multiple genes, and defining the potential of LRP1 to regulate these processes may assist in identifying molecules which could have significant therapeutic potential." (PMID 26061292, 2015). "By suppressing the inflammatory response of macrophages, LRP1 could also influence the development of atherosclerosis." (PMID 26061292, 2015). "Prior work has revealed that mice with a selective deletion of LRP1 in macrophages have more extensive atherosclerosis when crossed into an apoE/LDL receptor double knockout mouse or when bone marrow from LRP1-/- mice are transplanted into irradiated LDL receptor-deficient mice." (PMID 26061292, 2015). "However, in vitro studies indicate that muscle cell membrane LRP-1 appears to modulate some cellular processes involved in the pathogenesis of atherosclerosis and fibrosis such as inducing cell contraction and proliferation." (PMID 25514242, 2014). "The increase of LRP1 expression in OPA (mRNA and protein expression) suggest that LRP1 may play a crucial role in atherosclerosis progression, as previously demonstrated in other studies." (PMID 22828168, 2012). "In this view our results emphasize the importance for further investigating the impact of targeting hepatic LRP1 function in the apoE-mediated catabolism of TRL remnants in relation to postprandial dyslipidemia and the other risk factors affecting atherosclerosis development." (PMID 22701627, 2012). "Thus, LRP1 in SMCs functions cell autonomously in the maintenance of vascular wall integrity and protection from cholesterol-induced atherosclerosis." (PMID 19742316, 2009). "Therefore, atherosclerosis development can be mitigated via LRP1." (PMID 39524227, 2024). "Notably, it has recently been reported that the endocytic adaptor proteins known as epsins target ubiquitin-dependent internalization and downregulation of LRP1 in macrophages in hyperlipidemic conditions, hindering effective efferocytosis in macrophages and propelling atherosclerosis progression." (PMID 36247464, 2022). "Thus, the natural and synthetic agonists of LRP1 may be useful in treating atherosclerosis by inhibiting inflammation and promoting vascular cell survival, but additional evidence is needed to elucidate the associated mechanism." (PMID 34124208, 2021). "The role of LRP1 in VSMCs and macrophages in the development of atherosclerosis is different and opposite in vivo and in vitro, which may be the reason that the complexity of cross-talks among various signal pathways and different cell types and organ systems in vivo." (PMID 34124208, 2021). "Therefore, TTR may also play a protective role via LRP-1 receptor in atherosclerosis, especially because LRP-1 is involved in glucose homeostasis and inflammation, and binds HDL." (PMID 34359938, 2021). "However, in endothelial cells and adipocytes, LRP1 may promote resistance to atherosclerosis, primarily by inhibiting inflammation." (PMID 34124208, 2021).
atherosclerosis (continued). "Epsin-mediated LRP-1 degradation facilitated atheroma progression; however, whether epsins promote endothelial dysfunction through other protein interactions to contribute to the progression of atherosclerosis is unknown." (PMID 32770009, 2020). "Thus, LRP1 may protect against atherosclerosis by attenuating inflammation through a decrease in the cell-surface abundance of the TNF receptor-1, and also by inhibiting the Iκ-B kinase/NF-κB intracellular activation." (PMID 29914093, 2018). "In addition, macrophages with low LRP1 levels may contribute to the exacerbation of the inflammatory process, as it has been previously shown that macrophage LRP1 deficiency contributes to increased MMP‐9, MCP‐1 and TNF‐α secretion in atherosclerosis." (PMID 28378397, 2017). "A tissue-specific deletion of the Lrp1 gene in vascular SMC (smLRP1−/−) on a background of LDL receptor deficiency, causes smooth muscle cell proliferation, aneurysm formation, and a significant increase in susceptibility to cholesterol-induced atherosclerosis." (PMID 23922991, 2013). "Also concomitant LRP1 dysfunction could have an impact by multiple mechanisms on atherosclerosis development, which is more frequently observed in type III hyperlipidemia patients." (PMID 22701627, 2012). "LRP1 may function as an integrator of proliferative and anti-proliferative signals that control physiological mechanisms common to the pathogenesis of Marfan syndrome and atherosclerosis, and this is essential for maintaining vascular wall integrity." (PMID 17505534, 2007). "However, the opposite result has been observed in other studies, indicating that LRP1 mediates aggLDL uptake to induce high intracellular cholesteryl ester accumulation in VSMCs, causing the formation of VSMC-derived foam cells and promoting atherosclerosis progression." (PMID 34124208, 2021). "Therefore, gene therapy and recombinant LRP1 could be used to treat and prevent atherosclerosis." (PMID 34124208, 2021). "Moreover, a study showed that LRP1-dependent BMPER signaling is required for LPS-induced nuclear factor of activated T cells 1 (NFATc1) activation to induce acute inflammatory responses in endothelial cells, which may cause the initiation of atherosclerosis." (PMID 34124208, 2021). "LRP1 can promote the formation of VSMC-derived foam cells, leading to the progression of atherosclerosis." (PMID 34124208, 2021). "Thus, in VSMCs, LRP1 may exert two different and opposing effects on atherosclerosis." (PMID 34124208, 2021). "However, other studies have shown that LRP1 may be an atheroprotective factor for the development of atherosclerosis, as it has been reported that mice macrophage LRP-1 deficiency increases cell death and inflammation by impairing phosphorylated Akt activation and efferocytosis." (PMID 29914093, 2018). "One of the atheroprotective roles of LRP1 in the vascular wall is the regulation of the well-established mitogenic pathway mediated by platelet derived growth factor (PDGF), which promotes atherosclerosis." (PMID 29144234, 2017). "Studies from our laboratory have shown that LRP1 suppresses PDGF receptor β (PDGFRβ) activation and protects against atherosclerosis." (PMID 19742316, 2009). "Although LRP1 and ABCA1 therefore both play import ant and distinct roles in cellular cholesterol homeostasis and atherosclerosis, the functional interaction between these two membrane proteins has never been investigated." (PMID 19718435, 2009).
atherosclerosis (continued). "Interestingly, it has been shown that deletion of LRP1 induces CCR7 expression in M1 macrophages and promotes atherosclerosis regression." (PMID 36247464, 2022). "The lack of LRP1 in smooth muscle cells accelerates cholesterol-induced atherosclerosis as well as promotes injury-induced neointimal hyperplasia and vascular cardiomyopathy in a cholesterol-independent manner." (PMID 33548224, 2021). "The absence of LRP1 in mature adipocytes impairs lipid accumulation to limit diet-induced adiposity but also promotes inflammation in exacerbation of atherosclerosis." (PMID 33548224, 2021). "Probably more surprising, for established plaque, the lack of LRP1 expression in macrophages unexpectedly promotes atherosclerosis regression." (PMID 34124208, 2021). "Future preclinical studies should analyse whether modified EVs loaded with a low expression of APOB and FL and an overexpression of LRP1 and MBL2 could reduce atherosclerosis formation." (PMID 33374290, 2020). "The endocytic function and signaling properties confer a major role to LRP1 in the pathophysiology of numerous diseases such as hepatic steatosis, kidney fibrosis, acute respiratory distress syndrome (ARDS), Alzheimer's disease (AD) and atherosclerosis." (PMID 31080804, 2019). "While the exact mechanisms by which macrophage LRP1 modulates atherosclerosis and vascular remodeling are not fully understood, several possibilities exist." (PMID 26061292, 2015). "Third, LRP1 also modulates a number of signaling pathways, including the PDGF-signaling pathway, as well as the Wnt-signaling pathway, both of which impact the development of atherosclerosis." (PMID 26061292, 2015). "The data suggest that in the absence of apoE impaired LRP1 function correlates with improved atherosclerosis outcome." (PMID 22701627, 2012). "In the present study, we investigated the in vivo impact of LRP1 dysfunction on lipid metabolism and atherosclerosis development in the absence of apoE." (PMID 22701627, 2012). "Deletion of LRP1 within macrophages has been shown to enhance the extent of atherosclerosis in LDL receptor/apoE double knockout mice and in LDL receptor knockout mice receiving a bone marrow transplant from mice in which LRP1 was selectively deleted in macrophages." (PMID 22174911, 2011). "Macrophage LRP1 is known to influence the development of atherosclerosis, but its role in vascular remodeling has not been investigated." (PMID 22174911, 2011). "Currently, the mechanism by which macrophage LRP1 impairs lesion development in atherosclerosis is not understood." (PMID 22174911, 2011). "Our findings suggest that PI3K is the main driving force that promotes SMC proliferation and migration, elastolysis, spontaneous atherosclerosis and lesion progression in the absence of LRP1." (PMID 19742316, 2009). "The deletion of Lrp1 from smooth muscle cells also impacts the integrity of the vasculature by altering PDGFR β signaling and levels of various ECM molecules pivotal for proper vessel development, contributing to the development of hypertension, atherosclerosis and other cardiovascular diseases." (PMID 30931303, 2019). "First, in the vasculature, LRP1 regulates the TGF-β signaling pathway by suppressing TGF-β2 gene expression and regulates TGF-β2 protein levels by binding and removing this ligand upon endocytosis, which may influence the progression of atherosclerosis." (PMID 26061292, 2015). "The fact that excessive cholesterol accumulation in LRP1-expressing macrophages does not exacerbate the development of atherosclerosis likely results from the multifunctional nature of LRP1, which binds over 30 distinct ligands and influences numerous signaling pathways." (PMID 26061292, 2015).
atherosclerosis (continued). "We therefore decided to test, whether activation of PPARγ by rosiglitazone, a compound of this class that is in clinical use, might result in reduced nuclear accumulation of pSmad2 and suppression of atherosclerosis in mice lacking LRP1." (PMID 17505534, 2007). "Whether phosphorylation of LRP1 plays a role in preventing atherosclerosis is not understood." (PMID 29144234, 2017). "Consequently, disabling LRP1 tyrosine phosphorylation resulted in enhanced macrophage intracellular lipid accumulation and decreased clearance of apoptotic cells, thus resulting in accelerated atherosclerosis independent of plasma cholesterol levels." (PMID 29144234, 2017). "Determination of the in vivo significance of LDL receptor-related protein 1 (LRP1) dysfunction on lipid metabolism and atherosclerosis development in absence of its main ligand apoE." (PMID 22701627, 2012).
glioma (69 papers, 2011 to 2025). A benign or malignant brain and spinal cord tumor that arises from glial cells (astrocytes, oligodendrocytes, ependymal cells). "As a result, when the effects of LRP1 mRNA abundance on patient survival were examined, considering all gliomas comprehensively (grades 2+3+4), high levels of LRP1 mRNA were significantly associated with improved patient survival." (PMID 29088295, 2017). "Shruthi and collaborators explored the correlation between LRP1 expression, glioma cells' cholesterol content, and the tumor's aggressiveness." (PMID 39276062, 2024). "Low-density lipoprotein receptor-related protein-1 (LRP1) is frequently present in human glioma cells and the blood-brain barrier (BBB), which makes it a promising target for treating glioblastoma." (PMID 39861688, 2024). "Elevated LRP1 expression, which indicates poor prognosis in bladder cancer (BLCA), OC, low-grade gliomas (LGG), and glioblastoma (GBM), was also associated with immune infiltration in several other cancers." (PMID 39063239, 2024). "LRP1 has signal transduction activity and is widely distributed on the surface of tumor cells, such as myeloma, breast cancer, glioma, and melanoma cells." (PMID 36678620, 2023). "The nanoparticles are aggregated in glioma through specifically binding with low-density lipoprotein receptor-related protein-1 (LRP-1) highly expressed on the surface of brain microvascular endothelial cells and glioma cells." (PMID 36597214, 2023). "LRP-1 has been reported to be highly expressed in most gliomas, and its silencing found to significantly decrease An2 uptake in vitro in a U87 glioma cell model." (PMID 36430705, 2022). "The limited numbers of in-vitro studies on various glioma cell lines revealed a considerable degree of variability of LRP-1 mRNA expression with significantly higher levels in SF-539, U-87 MG, and U-343 MG cells lines." (PMID 36267880, 2022). "They added angiopep-2 on LMNVs to target the low-density lipoprotein receptor-related protein 1 (LRP1, overexpressed on the glioma cell surface) and promote blood-brain barrier penetration." (PMID 35656308, 2022). "The glioma cells overexpressed low-density lipoprotein receptor-related protein-1 (LRP1), which specifically binds to the linker-conjugated angiopep-2." (PMID 36425579, 2022). "The linker conjugated angiopep-2, which can specifically bind to the low-density lipoprotein receptor-related protein-1 (LRP1) overexpressed on glioma cells." (PMID 32508641, 2020). "Firstly, angiopep-2 allowed the nanoparticles to cross the BBB through RMT by recognition of LRP1 on the BBB and, secondly, angiopep-2 increased the accumulation of nanoparticles in glioma cells thanks to recognition of the LRP1 on the glioma cells surface." (PMID 32551212, 2020). "This strategy was used to improve the delivery of HCQ and sonoactive chlorin e6 to glioma tumors using angiopep-2 peptide-modified liposomes that target low-density lipoprotein receptor-related protein 1 (LRP1)." (PMID 33396545, 2020). "Previous studies on vascular smooth muscle cells, glioma and lung carcinoma cells showed that expression of LRP1 was negatively regulated by miR-205." (PMID 29507659, 2018). "This correlation, however, most likely reflects LRP1 functioning as a surrogate biomarker for low-grade gliomas." (PMID 29088295, 2017). "In this dataset, the absolute abundance of LRP1 mRNA was decreased in grade-4 gliomas or glioblastomas, compared with grade-2 and grade-3 gliomas." (PMID 29088295, 2017).